PCDH7 (protocadherin 7)
Diseases named in the same sentence as PCDH7 in open-access papers (continued):
Sharing a sentence is not in itself a finding about the gene and the disease.
Rett syndrome (7 papers, 2011 to 2025). A severe neurodevelopmental disorder affecting the central nervous system.
colon cancer (5 papers, 2021 to 2024). "For example, knockdown of protocadherin 7 (PCDH7) affects autophagy and induces ferroptosis, which enhances the sensitivity of colon cancer cells to chemotherapy by inhibiting the MEK1/2/ERK/c-FOS axis." (PMID 37007121, 2023). "In colon cancer, oncogenic lncRNA LNAPPCC promotes metastasis and recurrence and contributes to bad prognosis via forming a positive feedback loop with PCDH7." (PMID 34707942, 2021). "PCDH7 provides a potential therapeutic strategy in colon cancer: it can inhibit the MEK1/2/ERK/c-Fos axis by knocking down PCDH7, induce neurogenesis and autophagy, and enhance the effect of colon cancer cells on chemotherapy." (PMID 38167455, 2024).
prostate carcinoma (5 papers, 2013 to 2025). A carcinoma that arises from epithelial cells of the prostate gland. "Increased PCDH7 protein expression was observed during tumor progression in prostate cancer tissues and male TRAMP mice (which spontaneously develop prostate tumors following the onset of puberty)." (PMID 33963380, 2021). "Differential expression analysis between androgen-dependent and androgen-independent cell lines found the protocadherin gene PCDH7 to have the largest fold change, suggesting it may play a role in the development of castrate-resistant prostate cancer." (PMID 23826159, 2013).
bladder cancer (4 papers, 2016 to 2023). "For bladder cancer patients, the expression of PCDH7 in tumor tissues should be detected after surgery." (PMID 27070091, 2016). "Recent studies indicated that PCDH7 is frequently inactivated by DNA methylation in bladder cancer and functions as a tumor suppressor." (PMID 27070091, 2016). "The human PCDH7 gene is localized in chromosome 4p15, which is often inactivated in human cancers, including bladder cancer." (PMID 27070091, 2016). "Moreover, reduced PCDH7 expression has been found in colorectal 44 and bladder cancers." (PMID 35280687, 2022).
cervical cancer (4 papers, 2022 to 2025). A primary or metastatic malignant neoplasm involving the cervix. "Meanwhile, in cervical cancer, up-regulation of PCDH7 can significantly inhibit the proliferation, migration, and invasion of cancer cells, and PCDH7 is positively correlated with the survival rate of patients." (PMID 38167455, 2024). "PCDH7 is known to be downregulated in cervical cancer tissues and cell lines as compared to their corresponding controls, and the overexpression of PCDH7 markedly inhibits the migration and invasion abilities of cervical cancer cells." (PMID 35647198, 2022).
lung adenocarcinoma (4 papers, 2021 to 2026). A carcinoma that arises from the lung and is characterized by the presence of malignant glandular epithelial cells. "We identified an important oncogenic role for protocadherin 7 (PCDH7), a cell surface protein frequently overexpressed in lung adenocarcinoma and associated with poor clinical outcome." (PMID 42234744, 2026). "Protocadherin 7 (PCDH7) is known to be often overexpressed in lung adenocarcinomas." (PMID 34781949, 2021).
non-small cell lung carcinoma (4 papers, 2020 to 2026). A group of at least three distinct histological types of lung cancer, including non-small cell squamous cell carcinoma, adenocarcinoma, and large cell carcinoma. "PCDH7 induces MAPK signaling in non-small cell lung cancer, and its expression is associated with poor prognosis." (PMID 32694982, 2020). "Previous studies have found that PCDH7 expression was significantly upregulated in human non-small cell lung cancer (NSCLC)." (PMID 37063257, 2023). "For example, in human non-small cell lung cancer, PCDH7 was frequently overexpressed and functioned as an oncogene to induce cellular transformation and promote lung tumorigenesis by potentiating MAPK signaling." (PMID 35280687, 2022). "Intriguingly, expression of PCDH7 and PCDH10, which are generally considered to be tumor suppressor genes, has been proven necessary for the tumorigenicity of non-small cell lung cancer and glioblastoma, respectively." (PMID 32694982, 2020).
glioma (3 papers, 2019 to 2022). A benign or malignant brain and spinal cord tumor that arises from glial cells (astrocytes, oligodendrocytes, ependymal cells). "Primarily, miR-155-3p acts as an oncogene via the direct inhibition of tumour suppressors such as TP53INP1 (adenocarcinoma), FBXW7 (hepatocellular carcinoma), PCDH7/CREB3/SIX1 (glioma), WDR82 (colorectal cancer) and CADM1 (breast cancer)." (PMID 35611569, 2022). "Protocadherin-7 (PCDH7) and protocadherin-9 (PCDH9) were identified and experimentally validated as targets of miR-155-3p and miR-155-5p, respectively, within primary glioma cells." (PMID 35611569, 2022). "High GNAI, EMP3, TIMP1, ITGA5, and NMI while low PCDH7, CALCRL, and NFKBIA expressions could lead to poor prognoses in glioma patients." (PMID 35647198, 2022).
sarcopenia (3 papers, 2023 to 2025). Progressive decline in muscle mass due to aging which results in decreased functional capacity of muscles. "Studies have shown that PCDH7 plays a critical role in muscle development and atrophy, particularly in the progression of sarcopenia." (PMID 41445675, 2025). "Those patients with sarcopenia, osteoporosis, and osteosarcopenia had a significantly higher PCDH7 expression in both mRNA and protein levels than patients without sarcopenia and osteoporosis." (PMID 37476411, 2023). "By using the bioinformatic methods, this study identified PCDH7 as the crosstalk gene that bridges sarcopenia and osteoporosis—validated by real-time quantitative PCR and Western blot on clinical samples." (PMID 37476411, 2023). "This suggests that PCDH7 must play a role in the development of both sarcopenia and osteoporosis—but how?" (PMID 37476411, 2023). "Gene expression and protein levels were detected and compared; consistent with the results, patients with sarcopenia, osteoporosis, or both have a significantly higher level of PCDH7 than healthy adults." (PMID 37476411, 2023). "To prove the relationship between PCDH7 and osteosarcopenia, we collected clinical samples of patients with sarcopenia, osteoporosis, both sarcopenia and osteoporosis, and patients without sarcopenia or osteoporosis." (PMID 37476411, 2023). "PCDH7 seems to be a key gene related to the development of both sarcopenia and osteoporosis." (PMID 37476411, 2023). "Only PCDH7 was validated in both sarcopenia and osteoporosis test datasets." (PMID 37476411, 2023). "Finally, PCDH7 was identified and validated as the gene that may be significantly related to the co-occurrence of sarcopenia and osteoporosis." (PMID 37476411, 2023). "Of four key crosstalk genes (ARHGEF10, PCDH7, CST6, and ROBO3), PCDH7 was identified and validated as relating the development of both sarcopenia and osteoporosis." (PMID 37476411, 2023). "The relationships between PCDH7 and sarcopenia, as well as osteoporosis, are not fully understood." (PMID 37476411, 2023).
Stroke (3 papers, 2021 to 2024). Sudden impairment of blood flow to a part of the brain due to occlusion or rupture of an artery to the brain. "Only one gene—PCDH7—was associated with the incidence of stroke." (PMID 37895035, 2023). "In hypertensive African Americans who suffer from a higher stroke burden due to hypertension, PCDH7 is a plausible genetic determinant for stroke incidence." (PMID 38474013, 2024). "While none of our findings were directly replicated, their gene level associations with stroke warrant future replication efforts, particularly variants located in or near the NTM or PCDH7 genes." (PMID 34992631, 2021).
colorectal tumor (2 papers, 2021 to 2023). "detected the decreasing expression of PCDH7, known for its involvement in the intercellular connections, in the colorectal tumour tissues." (PMID 34613665, 2021).
gastric adenocarcinoma (2 papers, 2021 to 2024). "F5 exhibits an expression of 5.89 in gastric adenocarcinoma, surpassing PCDH7 in terms of the lowest expression in GC." (PMID 39456895, 2024). "Pcdh7 was originally identified from Xenopus embryo, termed NF-protocadherin (NFPC), followed by the cloning of human ortholog PCDH7 from the human gastric adenocarcinoma cell." (PMID 34884920, 2021).
liver disorder (2 papers, 2019 to 2025). A disease involving the liver. "Thus, the PCDH7 gene can be responsible for liver disorders." (PMID 31438838, 2019). "Activated HSCs also upregulate α-SMA and become contractile through protocadherin 7 (PCDH7) and may thereby contribute to portal hypertension." (PMID 40595432, 2025).
membranous nephropathy (2 papers, 2021 to 2024). "Very recently, antibodies against protocadherin 7 (PCDH7) and high termperature recombinant protein A1 /HTRA1), both of IgG4 subclass, were described in several patients with anti-PLA2R-negative primary membranous nephropathy." (PMID 33828546, 2021).
adenoma (1 paper, 2013). A neoplasm arising from the epithelium. "For the classical adenomas on the tissue microarray, 83/85 (97.6%) demonstrated strong expression of PCDH7, and 2/85 (2.4%) loss of expression." (PMID 23671423, 2013). "For PCDH7, 12/32 (37.5%) SAs had methylation (12/29 SSAs, 0/1 mixed SSA/TSA, 0/2 TSA), whereas none of the classical adenoma (0/10) samples and 1/5 (20%) of the normal mucosa samples were methylated." (PMID 23671423, 2013).
brain cancer (1 paper, 2023). A primary or metastatic malignant neoplasm affecting the brain. "Cx43 gap junctions between metastatic brain cancer cells and astrocytes are favored by the over expression of the brain specific cell adhesion molecule protocadherin 7 (PCDH7) in metastatic cells." (PMID 38293652, 2023).
genetic generalized epilepsy (1 paper, 2025). A generalized epilepsy that is understood to have a genetic etiology. "The association of PCDH7 with genetic generalized epilepsy prompted us to investigate whether our Pcdh7 mouse model exhibits seizures." (PMID 40870033, 2025).
intraepithelial neoplasia (1 paper, 2020). A precancerous neoplastic process that affects the squamous, glandular, or transitional cell epithelium without evidence of invasion. "In this cancer, PCDH7 immunoexpression showed a gradual reduction in the normal tissue to intraepithelial neoplasia and GC, and an even lower immunoexpression in CG lymph node metastasis." (PMID 33369468, 2020).
ischemic stroke (1 paper, 2021). A stroke disorder caused by obstruction of blood flow to the brain, due to thrombotic (local blood clot formation) or embolic (due to a blood clot or other material traveling from another site) event. "In previous studies, PCDH7 was differentially expressed in aneurysm wall tissue compared to superficial temporal artery tissue, as well as being associated with white matter hyperintensities in EAs with ischemic stroke." (PMID 34992631, 2021).
liver fibrosis (1 paper, 2019). "In a study with humans, PCDH7 was reported as a hepatic stellate cell surface marker and hepatic stellate cells play important role in the occurrence of liver fibrosis." (PMID 31438838, 2019).
neuroblastoma (1 paper, 2011). Neuroblastoma (NB) is the most common solid, extracranial childhood tumor.
osteoporosis (1 paper, 2023). A condition of reduced bone mass, with decreased cortical thickness and a decrease in the number and size of the trabeculae of cancellous bone (but normal chemical composition), resulting in increased fracture incidence. "However, few studies have reported whether PCDH7 plays a role in muscle development and atrophy, as well as whether PCDH7 contributes to the development of osteoporosis." (PMID 37476411, 2023).
ovarian carcinoma (1 paper, 2022). A malignant neoplasm originating from the surface ovarian epithelium. "We also identified the additional CTCFL targets ACTBL2, MALT1, and PCDH7 to be predictive for ovarian cancer treatment outcomes." (PMID 35132075, 2022).
pancreatic cancer (1 paper, 2025). "Among the nineteen UDEGs, other than the seven UDEGs reported to be carcinogenic and prometastatic genes involved in pancreatic cancer, the other UDEGs, such as ESM1, PCDH7, CORO2A, CEACAM5, GALNT5 and TMPRSS4, are also involved in other cancers." (PMID 40362181, 2025).
parasite infection (1 paper, 2024). "For instance, PCDH7 is a potential biomarker for host resistance to parasite infection, while CDH26 regulates leukocyte activation and adhesion during allergic reactions." (PMID 38982349, 2024).
rectal cancer (1 paper, 2021). A primary or metastatic malignant neoplasm that affects the rectum. "According to literature validation, we detected some rectal cancer‐related mRNAs including PRKCB, NCAM1, ZEB1, PCDH7, Cav1 and FGF2 in the subnetwork." (PMID 34613665, 2021).
steatosis (1 paper, 2020). Increased lipid within the cytoplasm of cells. "The expression profiles of profibrotic genes such as CYGB, ACTA2, PCDH7, DES, COL1A1, and COL1A3 were also significantly up‐regulated in the co‐culture NASH model, when compared with the steatosis model." (PMID 31909357, 2020).
triple-negative breast carcinoma (1 paper, 2021). An invasive breast carcinoma which is negative for expression of estrogen receptor (ER), progesterone receptor (PR), and human epidermal growth factor receptor 2 (HER2). "Additionally, when triple-negative breast cancer cells migrate to the brain, astrocytes activate the S100A4-related pathway (protocadherin 7 (PCDH7)-PLCβ-Ca2+-CaMKII/S100A4)." (PMID 33806911, 2021).
cancer (48 papers, 2016 to 2026). A tumor composed of atypical neoplastic, often pleomorphic cells that invade other tissues. "Although most studies on PCDH7 have focused on its role in cancer, some studies in recent years have linked PCDH7 to central nervous system disorders." (PMID 38474013, 2024). "Furthermore, in CC, decreased expression of PCDH7 was linked to cancer cell metastasis, migration and invasion." (PMID 36905477, 2023). "Together, these data suggest that the exact roles and underlying mechanisms of PCDH7 in hoCIC formation and human cancers may only be addressed in a confined model system." (PMID 32457908, 2020). "Also, our study found that PCDH7 was highly expressed in tumor tissues and was associated with poor prognosis, with all these findings suggesting that PCDH7 might be an important cancer-promoting factor." (PMID 36117156, 2022). "The interaction between protocadherin 7 (PCDH7) on cancer cells and Cx43 on astrocytes facilitates the creation of these gap junctions." (PMID 39780275, 2025). "Most of the existing literature on PCDH7 focuses on its function during cancer progression, with only one study suggesting that PCDH7 regulates dendritic spine morphology and synaptic function via interaction with GluN1." (PMID 40870033, 2025). "PCDH7, known as protocadherin 7, is a subfamily of the cadherin superfamily and plays biological roles in multiple cancer types." (PMID 41169393, 2025). "Most studies on PCDH7 have focused on its role in cancer, despite reports that, like most PCDHs, it is highly expressed in the nervous system." (PMID 40870033, 2025). "Subsequently, PLA2R, PCDH7, HTRA1 and FAT1 antigens were found to be positive in patients with malignancy-associated MN." (PMID 38686366, 2024). "Protocadherin 7, expressed by breast and lung cancer cells, promotes the polymerization of cancer cell–astrocyte gap junctions consisting of connexin 43 (CX43), enabling the transfer of cGAMP from cancer cells to astrocytes." (PMID 38525112, 2024). "Through RNA-Seq analysis of HNSCC samples (3 tumors and 3 para-carcinoma tissues), we identified 8 pivotal marker genes (PCDH7, CDH2, ITGA3, SEMA7A, TMEM132A, CD276, TMEM2, GPR158) that were overexpressed in tumor specimens." (PMID 38548747, 2024). "There have been many studies showing that PCDH7 is abnormally expressed in various cancers and has a carcinogenic or anti-tumor effect." (PMID 37063257, 2023). "Previous studies have found that protocadherin 7 (PCDH7) is aberrantly expressed in several cancers and exerts pro- or anti-tumor effects." (PMID 37894938, 2023). "For instance, the most highly and significantly upregulated gene upon GPR81 KD was Protocadherin H7 (PCDH7) which belongs to the cadherin superfamily of cell–cell adhesion proteins and is assigned context-dependent roles in various cancers." (PMID 37993804, 2023). "Then, a series of in vitro experiments was performed, which verified the cancer-promoting role of PCDH7 in NSCLC." (PMID 37538171, 2023). "We reported recurrent methylation changes in the promoters of several genes, many previously implicated in cancer, including FAM83A and SEPT9 (hypomethylation), as well as PCDH7, NKX2-1, and SOX17 (hypermethylation)." (PMID 37742993, 2023). "Protocadherin-7 (PCDH7) is regarded as a potentially targetable surface molecule in cancer cells and plays an important role in their proliferation, metastasis, and drug resistance." (PMID 37063257, 2023). "Protocadherin 7 (PCDH7) promotes the assembly of carcinoma-astrocyte gap junctions, which produces IFNα, which can activate nuclear factor κB (NF-κB) pathways." (PMID 37957639, 2023). "Cancer cells express protocadherin 7 (PCDH7), promote carcinoma-astrocyte gap junctions, which then induces IFNα and TNF production and activation of STAT1 and NF-κB pathways in cancer cells to support brain metastasis." (PMID 33442395, 2021). "Protocadherin 7 (PCDH7) directly interacts with Cx43 to assemble functional gap junctions between cancer cells and astrocytes." (PMID 34504845, 2021).